LEFTY1 (left-right determination factor 1)
Description:
Required for left-right axis determination as a regulator of LEFTY2 and NODAL.
Synonyms: LEFTB; LEFTYB
Tractability: Antibody: UniProt places it where antibodies can reach, with medium confidence; UniProt predicts a signal peptide or a membrane-spanning region; its Gene Ontology location is reachable by antibodies, with medium confidence.
Gene: Protein-coding gene on chromosome 1 (225,886,279 to 225,911,382, reverse strand). Ensembl gene ENSG00000243709.
Subcellular location: Secreted
Pathways (Reactome):
Developmental Biology: Regulation of signaling by NODAL; Signaling by NODAL
Gene Ontology:
Molecular function: cytokine activity; growth factor activity; transforming growth factor beta receptor binding
Biological process: anterior/posterior axis specification; BMP signaling pathway; determination of left/right symmetry; heart morphogenesis; negative regulation of transcription by RNA polymerase II; transforming growth factor beta receptor signaling pathway
Cellular component: extracellular region
Genetic constraint (gnomAD): Loss-of-function variants: 20 observed, 20.08 expected, observed/expected ratio (o/e) 1, 90% interval 0.7 to 1.45. The upper end of that interval is the gene's LOEUF score, 1.45, which puts it in group 5 of 6, group 1 being the genes least tolerant of losing a copy. Missense variants: 414 observed, 443.04 expected, observed/expected ratio (o/e) 0.93, 90% interval 0.86 to 1.01. Synonymous variants: 201 observed, 203.15 expected, observed/expected ratio (o/e) 0.99, 90% interval 0.88 to 1.11.
Homologues: Orthologues: chimpanzee LEFTY1 (99% identical), macaque PYCR2 (95% identical), mouse Lefty2 (83% identical), pig LEFTY2 (82% identical), mouse Lefty1 (82% identical), rat Lefty1 (82% identical), rat Lefty2 (80% identical), dog LEFTY1 (54% identical), tropical clawed frog lefty1 (36% identical), zebrafish lft2 (35% identical), zebrafish lft1 (34% identical). Paralogues in human: LEFTY2 (96% identical), BMP10 (20% identical), TGFB1 (19% identical), BMP2 (19% identical), BMP4 (19% identical), TGFB2 (19% identical), GDF11 (19% identical), GDF6 (19% identical), INHBB (19% identical), GDF2 (18% identical), TGFB3 (18% identical), GDF1 (18% identical), and 19 more.
Diseases named in the same sentence as LEFTY1 in open-access papers:
LEFTY1 is named in the same sentence as 25 diseases in open-access papers, as found by Europe PMC text mining. Sharing a sentence is not in itself a finding about the gene and the disease. The quoted sentences say what the papers report.
colorectal cancer (2 papers, 2023 to 2024). A primary or metastatic malignant neoplasm that affects the colon or rectum. "In particular, the downregulation of EPHB2 and LEFTY1 and upregulation of NUPR1 genes known to be associated with colorectal cancer were observed, suggesting their involvement in tumorigenic microenvironment." (PMID 39285481, 2024). "The downregulation of EPHB2, involved in cell cycle processes, and LEFTY1, involved in intestinal mucosal immunity and TGF-β signaling, is a common feature also observed in colorectal cancers and Crohn’s disease, respectively." (PMID 39285481, 2024).
diabetes (2 papers, 2015 to 2021). "Genetics are heavily linked to the susceptibility of T2D and the comparison of the NZO and B6-ob/ob genomes lead to the identification of several diabetes genes like Lefty1, Apoa2, Pcp4l1 and others." (PMID 34445304, 2021). "Lefty1, one candidate exclusively expressed in islets of diabetes-resistant B6-ob/ob mice, is an atypical member of the TGF-β family that inhibits Nodal by direct binding to Nodal." (PMID 26348837, 2015). "We found that two SNPs in human LEFTY1 were nominally associated with altered insulin release in a glucose tolerance test, but not with glycaemia or diabetes." (PMID 26348837, 2015). "Accordingly, the lower expression of Smad3 in B6-ob/ob islets as a consequence of the presence of Lefty1 could trigger beta-cell proliferation in this diabetes-resistant model." (PMID 26348837, 2015). "In summary, our data indicate that Lefty1, Apoa2, Pcp4l1 and Ifi202b modify beta-cell proliferation, and suggest that the alteration of their expression contributes to the development of severe diabetes in the NZO mouse strain." (PMID 26348837, 2015).
ovarian carcinoma (2 papers, 2016 to 2024). A malignant neoplasm originating from the surface ovarian epithelium. "We found that a low expression level of CDKN2B and WNT11 was associated with longer survival in ovarian cancer patients, while high expression levels of SMAD3, ZFYVE16, BMP6, LEFTY1, and DVL2 were significantly associated with poor survival." (PMID 38403634, 2024). "Despite the potential tumour-suppressor characteristics of LEFTY1 and the specific abundance profile of this protein, there is currently limited knowledge linking its expression to the pathology of ovarian cancer histotypes." (PMID 27713570, 2016). "In a western blot analysis of a panel of ovarian cancer cell lines of validated histotype; the majority of CCC cell lines showed high expression of CTH and LEFTY1." (PMID 27713570, 2016).
adenoma (1 paper, 2025). A neoplasm arising from the epithelium. "Similar to our results, adenoma-specific stem cells were shown to originate from TIC-like populations expressing ETS2, SLC12A2, and LEFTY1." (PMID 41282138, 2025).
Barrett’s oesophagus (1 paper, 2018). "We find that cell populations in Barrett’s oesophagus, marked by LEFTY1 and OLFM4, exhibit a profound transcriptional overlap with oesophageal submucosal gland cells, but not with gastric or duodenal cells." (PMID 30323168, 2018).
cardiac hypertrophy (1 paper, 2023). "Lefty1 knockdown upregulated the expression of fibrosis‐related genes and Nppb, indicating that Lefty1 plays a crucial role in alleviating fibrosis and cardiac hypertrophy." (PMID 37482908, 2023).
Carpenter syndrome (1 paper, 2025). An extremely rare autosomal recessive syndrome characterized by premature closure of cranial sutures leading to cone-shaped head, fusion of the digits, and the presence of more digits than normal. "In RAB23-deficient mice, which mimic Carpenter syndrome in humans, the lack of functional RAB23 results in overt FGF10, Hh and Nodal signaling with consequent misexpression of downstream signal transducers (pERK1/2, Gli1, Lefty1/2 and Pitx2)." (PMID 40261407, 2025).
endometriosis (1 paper, 2025). The growth of functional endometrial tissue in anatomic sites outside the uterine body. "Our results agree with that finding and suggest that the higher LEFTY1 expression in the EEM group could contribute to endometriosis-related infertility." (PMID 40698088, 2025). "Healthy endometrium does not express LEFTY1 during the implantation window, while the endometrium of women suffering from endometriosis as well as infertility showed its expression." (PMID 40698088, 2025). "BIRC3, CEL, and LEFTY1 were significantly less expressed in the endometrium of women with endometriosis than without (logFC = −0.79, p = 0.0051; logFC = −0.52, p = 0.0051; logFC = −0.61, p = 0.0099, respectively)." (PMID 40698088, 2025).
hepatic carcinoma (1 paper, 2017). "For example, TGF-β1 reduced LEFTY1 CpG island shore methylation by about 10 to 20%, resulting in increased LEFTY expression in human pancreatic and hepatic carcinoma cells." (PMID 28969018, 2017).
myocardial infarction (1 paper, 2023). Gross necrosis of the myocardium, as a result of interruption of the blood supply to the area, as in coronary thrombosis. "Consistent with the findings of this study, adenovirus‐mediated overexpression of Lefty1 has been shown to ameliorate myocardial infarction–induced cardiac fibrosis as well as TGF‐β1‐induced upregulation of Col1 and Col3 in neonatal rat cardiac fibroblasts." (PMID 37482908, 2023).
seminoma (1 paper, 2015). A radiosensitive malignant germ cell tumor found in the testis (especially undescended), and extragonadal sites (anterior mediastinum and pineal gland). "Furthermore, additional EC and pluripotency genes were upregulated (SOX2, LEFTY1 /2, DNMT3L, SALL4, DPPA5, BCAT1, FZD7, LIN28, ZIC3), while seminoma-associated genes where downregulated (SOX17, TFAP2C, cKIT, PRAME), without changing 5mC-levels." (PMID 26226633, 2015). "Among them, GDF3, NODAL, LEFTY1 /2, GAL, DPPA3, SOX2, DNMT3B /L, DPPA5, BCAT1, FGF2, PRDM14, ZIC3 and FZD7, while seminoma markers SOX17, cKIT and PRAME were downregulated." (PMID 26226633, 2015).
testicular teratoma (1 paper, 2023). "The Nodal antagonist Lefty1 and Lefty2 are other possible candidates to continue investigating the impact of microenvironment on testicular teratoma development." (PMID 37180974, 2023).
cancer (9 papers, 2010 to 2025). A tumor composed of atypical neoplastic, often pleomorphic cells that invade other tissues. "Within the top 20 genes ranked by Notch pathway-guided COCA, there are several genes related to differentiation (Tdgf1, Egr1 and Lefty1), cell growth (Ddit4, Hk2, Phlda2, Egln3 and Igfbp1) and tumor/cancer development (Afp, Sfrp2, Egr1, Hk2 and Phlda2)." (PMID 20353603, 2010). "LEFTY1 is a novel member of the TGF-beta superfamily and modulates the epithelial-mesenchymal transition and cancer stem cell properties in the context of OCCC." (PMID 37525249, 2023). "Taking the protein candidates with the highest (MSLN) and lowest (LEFTY1) expression in HGSC relative to the other histotypes and mapping these across other cancers revealed highly variable patterns of abundance between TCGA tissue type sets." (PMID 27713570, 2016). "Additionally, LEFTY1, LEFTY2, and GDF3 showed higher expression in iPSC lines than in cancer cells and MSC lines." (PMID 39621192, 2025).
tumor (8 papers, 2010 to 2025). "Upregulation of XIAP expression due to a loss of LEFTY1 causes a resistance to chemotherapy by tumor cells, resulting in tumor progression and recurrence." (PMID 28969018, 2017). "Our data corroborate findings in other systems in particular the observation that β-catenin can recruit LSD1 to regulate the expression of the tumor suppressor Lefty1 in mouse embryonic stem cells." (PMID 30894540, 2019). "Tumor-specific stem-like cells (tSTM, cluster 0) exhibited strong upregulation of OLFM4, LEFTY1, SOD3, LCN2, SLC12A2, and MMP7, consistent with proliferative, inflammatory, and invasive phenotypes." (PMID 41282138, 2025). "The study identified tumor initiating cells which express ETS2, SLC12A2 and LEFTY1." (PMID 41282138, 2025). "Similarly, HOXA10, LEFTY1, and MT1H have all been suggested to act as tumor suppressors, whose overexpression leads to a better prognosis." (PMID 32841292, 2020).
infection (3 papers, 2013 to 2025). The state of being infected such as from the introduction of a foreign agent such as serum, vaccine, antigenic substance or organism. "Infection of cells with the Lefty1, Pcp4l1, and Apoa2 encoding viruses increased BrdU incorporation by 87%, 80%, and 92%, respectively; overexpression of Ifi202b decreased the number of BrdU positive cells by 43%." (PMID 26348837, 2015). "In particular, the significant over-expression of the Csf1, Lefty1, Ccrl2, Gdf3, Il-10 and Ccl8 genes (1.8–5.8 fold increases) was seen at day 9 post-infection." (PMID 23861742, 2013). "Furthermore, LEFTY1 was upregulated in the decidualized spheroids and infection did not significantly impact its expression." (PMID 39666439, 2025). "Based on the RNA-seq analysis, we observed that in non-decidualized spheroids, infection led to an increased fold change expression of TNFSF18 and LEFTY1." (PMID 39666439, 2025).
LEFTY1 also shares sentences with these, for which no sentence is quoted: Crohn disease (2 papers); endometrial carcinoma (1); Infertility (1); lung fibrosis (1); melanoma (1); metastatic colorectal cancer (1); Obesity (1); prostate carcinoma (1); teratocarcinoma (1); ulcerative colitis (1).